ARG1 (arginase 1)
Diseases named in the same sentence as ARG1 in open-access papers (continued):
Sharing a sentence is not in itself a finding about the gene and the disease.
cancer (continued). "Since Arg1 can regulate the bioavailability of L-arginine, it can mediate dysregulated inflammation, the immune evasion of cancer cells, fibrosis, and immunosuppression." (PMID 33806290, 2021). "This is important because oral tongue cancers appear to behave differently from other cancers that are currently in clinical trials testing the treatment efficacy of ARG1 mimics." (PMID 34885177, 2021). "In the context of cancer, it is well accepted that suppressive myeloid cells can inhibit T-cell responses by producing the enzyme Arg-1." (PMID 34149350, 2021). "Currently, we have several methods to tackle MDSCs in cancer via targeting its expansion, infiltration, migration, activation, differentiation, Arg1 and iNOS induction, and so forth, which is reviewed detailedly in related reviews." (PMID 34957205, 2021). "LncRNAs also modulate immunosuppression and cancer progression through the regulation of ROS (reactive oxygen species), NO (nitric oxide), and ARG1 (arginase 1) production in MDSCs." (PMID 34123857, 2021). "Human Arginase 1 (hArg1) is an important therapeutic target for the treatment of various cancers, nervous system dysfunction, and cardiovascular dysfunction and diseases." (PMID 34326456, 2021). "Clinically, the upregulation of arginase activity and the expression of ARG1, has been correlated with various cancers, such as gastric, breast, renal cell, and head and neck squamous cell carcinomas." (PMID 34031449, 2021). "The results reported here provide the first demonstration that neutrophil exocytosis can induce ER stress-mediated apoptosis in cancer cells via the enzymatic activity of exocytosed arginase-1, which rapidly depletes arginine in the surrounding medium." (PMID 34131176, 2021). "ARG1 expression is substantially elevated in myeloid cells in cancer and mitigates antitumor responses via multiple mechanisms." (PMID 34504786, 2021). "The key enzymes of the urea cycle, Carbamoyl-phosphate synthase 1 (CPS1), Ornithine carbamoyl-transferase (OTC), and Arginase (ARG1) were highly expressed in the liver, but normal tissues were significantly higher than cancer tissues in most cases." (PMID 33869206, 2021). "Recent studies reported that the MDSCs profoundly decreased L-arginine levels in cancer by producing Arginase-1 (Arg-1), thus downregulating the activity of T cells at the site of action." (PMID 34834282, 2021). "Towards this, the therapeutic prowess of both ARG1 mimics and inhibitors are under investigation and in clinical trials that include various cancer types." (PMID 34885177, 2021). "We therefore analyzed the expression of mRNA for CD117 and the M2 markers IL-10, fibronectin-1 (FN1), and arginase 1 (ARG1) in total leukocytes from cancer patients and HDs." (PMID 34090509, 2021). "Here, we investigated the complexity of ARG1 metabolism in this cancer subsite to appreciate the therapeutic potential of this potential biological vulnerability." (PMID 34885177, 2021). "The RT-qPCR results demonstrated that both ZVI@Ag and ZVI@CMC NPs were able to enhance the expression of M1 marker iNOS but reduced the level of M2 marker Arginase-1 (Arg1) in BMDMs under the cancer cell co-culture condition." (PMID 34093872, 2021). "Many studies have in fact correlated overexpression of ARG1/2 and poor prognosis in a variety of cancers types." (PMID 33401460, 2021). "The stimulation with an Arg-1- derived peptide (ArgLong2, 38-mer, positions 169–206 in Arg-1) in vitro, strongly impacted responses against Arg-1 in healthy donors and cancer patients, rebalancing the microenvironment." (PMID 34960055, 2021).
cancer (continued). "Here, we have found that neutrophil arginase-1, released from activated human neutrophils or dead cells, induced apoptosis in cancer cells through an endoplasmic reticulum (ER) stress pathway." (PMID 34131176, 2021). "Arginase-1+ macrophages also promote wound-healing and decrease T cell activation and induce it when tolerance is sought or when targeting Arginase-1 in cancer is the focus of current efforts." (PMID 32849510, 2020). "Both, granulocytic myeloid-derived suppressor cells (G-MDSC) and conventional mature human polymorphonuclear neutrophil granulocytes (PMN) express high levels of arginase 1 and can act as suppressor cells of adaptive anti-cancer immunity." (PMID 33717053, 2020). "MDSC are cells of myeloid origin that emerge in almost all cancer types and are able to suppress T-cell functionality through several mechanisms such as the release of the arginine-degrading enzyme arginase-I (ARG1), ROS and prostaglandins." (PMID 32630667, 2020). "Our results showed that IDO and IL-10 mRNA levels were increased about 27.99 fold and 8.54 fold in cancer patients’ cells over control cells, respectively, but ARG1 levels were increased by 1.68 fold." (PMID 33679700, 2020). "As revealed by the findings of this study, in all groups, Arg-1 has been shown to be more sensitive to detection of cancer than HepPar-1." (PMID 32854754, 2020). "Degranulated neutrophils are also expanded in peripheral circulation of cancer patients, and ARG1 released from these cells strongly contributes to general suppression of T-cell functions." (PMID 32499785, 2020). "This is known for the well-described co-expression of Arg1 and iNOS in cancer, which allows peroxinitrite formation." (PMID 33392202, 2020). "The sensitivity of Arginase-1 for diagnosis of cancer in HBV infected patients was more than that of HepPar-1 (P < 0.001)." (PMID 32854754, 2020). "Arginase-1 is therefore an attractive target for the development of new drugs for cancer immunotherapy." (PMID 32647818, 2020). "Chronic stress, which frequently accompanies cancer, was reported to increase the generation of ARG1+ MDSCs in mice and humans, through catecholamines stimulating β2 adrenergic receptors (β2AR)." (PMID 32499785, 2020). "The dependence on arginase-1 and its regulation of the T cell receptor ζ chain was demonstrated using PBMCs from healthy donors and in cancer patients." (PMID 32983165, 2020). "Since metabolic changes occur during cancer development, we checked the modulation of Arg-1, NOS-2 and COX-2 expression, three key enzymes involved in tumorigenesis." (PMID 32138292, 2020). "Previous studies consistently show that MDSCs in PB contribute to the progression of various cancers by reducing T cell response via expression of iNOS, ARG1, and inflammatory cytokines." (PMID 32780544, 2020). "Arginase is mainly produced by MDSCs highly enriched in TME, and ARG1‐expressing MDSCs play a role in changing T‐cell response in cancer patients, enhancing immunosuppressive cell function, influencing immune network regulation, and influencing ICB efficacy." (PMID 32875727, 2020). "Arg-1 was better able to detect hepatocyte cells with a higher sensitivity and specificity which had led to improved cancer detection in hepatitis B infected patients." (PMID 32854754, 2020). "Elevated levels of Arginase-1 have been detected in tumors of patients with various types of cancer, with the highest levels in lung, gastrointestinal and bladder cancers." (PMID 32647818, 2020). "Mounting evidence indicates that MDSCs are enriched both locally and systemically during cancer growth in mice and humans, and their activation in pathological conditions upregulates Arg-1 and iNOS." (PMID 32063899, 2019). "Arginase 1 (Arg-1) was increased in resistant PBMCs, indicating a shift from M1 cancer-clearing macrophages to M2 immune-inhibitory macrophages." (PMID 31881743, 2019).
cancer (continued). "Depletion of arginine induced by PEGylated arginase 1 (ARG1) (BCT-100) has shown anticancer effects in arginine auxotrophic cancers that lack argininosuccinate synthetase (ASS1) and ornithine transcarbamylase (OTC)." (PMID 30808864, 2019). "MDSCs of HCV-infected individuals, although poorly characterized compared to those derived from cancer patients, are able to inhibit T cell proliferation mainly by means of ARG1 and ROS production." (PMID 31259160, 2019). "It seems that apoptosis and cell cycle arrest are the major mechanisms by which cancer cell growth is suppressed by PEGylated ARG1 treatment." (PMID 30808864, 2019). "MDSCs deplete Arg because they express high levels of ARG1, and their number increases 4–10 times depending on the type of cancer." (PMID 31354721, 2019). "PEGylated arginase 1 (BCT-100) was provided free-of-charge by Bio-cancer Treatment International Limited." (PMID 30808864, 2019). "We demonstrated that CD14+ARG1+ cells were significantly increased in cancer patients as compared to the HDs." (PMID 31533831, 2019). "Irrespective of the intracellular or extracellular Hsp70 content in the carcinoma cells, the F4/80 and arginase-1 level increased during co-cultivation." (PMID 31861801, 2019). "We characterized spontaneous immune responses against optimized 38-mere arginase-1-derived peptide epitope in cancer patients and healthy donors using ex vivo and in vitro IFNγ ELISPOT and intracellular staining for IFNγ and TNFα." (PMID 30400835, 2018). "We have previously identified arginase-1 hotspot region that contains multiple peptide epitopes commonly recognized by T cells from cancer patients and healthy donors." (PMID 30400835, 2018). "MDSC in cancer patients and in mice are well known to produce ROS, which can synergize with ARG1 in promoting immunosuppression." (PMID 29921770, 2018). "Human ARG1 is a key enzyme in the urea cycle, which is regarded as a potential therapeutics against cancer." (PMID 28765554, 2017). "Analysis of the RNA derived from the macrophages by qRT-PCR revealed that cancer cell conditioned media induced Arg1 expression in macrophages in an oncogenic Kras dependent manner." (PMID 28980940, 2017). "Cancer patient plasma samples were assessed for Arg1 protein and L-arginine by ELISA and mass spectrometry, respectively." (PMID 29254508, 2017). "l-Arginine depletion by arginase 1 and/or nitric oxide produced by granulocytes and myeloid-derived suppressor cells has been observed in certain cancers and infections." (PMID 28487700, 2017). "The therapeutic potential of targeting Arg1 was further supported in a screen of cancer patient samples that revealed an abundance of Arg1-expressing myeloid cells in tumors and high amounts of Arg1 in plasma." (PMID 29254508, 2017). "Taken together, these data show that EDA-FN enhances arginase-1 expression of myeloid cells, possibly contributing to immune suppression in cancer." (PMID 27653627, 2016). "Elevated levels of ARG1 and/or ARG2 expression have been implicated in immune cell dysfunction, infections, vascular diseases and many types of cancers (primarily ARG1)." (PMID 27363017, 2016). "In different mouse models of cancer, osteoblasts or EDA-FN was found to up-regulate arginase-1 expression in myeloid-derived cells, resulting in increased cancer growth." (PMID 27653627, 2016). "In our experiments, morphine prevented MMP-9 increase and arginase-1 induction in both models of activation (treatment with IL-4 and coculture with cancer cells) in RAW264.7 and BMM cells." (PMID 26078009, 2015). "Morphine decreased the cancer cell coculture- or IL-4-induced expression of arginase-1 in RAW264.7 or bone marrow derived macrophages." (PMID 26078009, 2015). "Arg1 appears to be a major mediator of T cell suppression in both Gr-MDSCs and PMNs in cancer patients." (PMID 25014230, 2014). "Others demonstrated that ARG1-producing MDSCs are granulocytic and they are increased in the circulation of human cancers." (PMID 24741628, 2014).
cancer (continued). "Since Arg1 appears to be the major mediator of T cell suppression by both Gr-MDSCs and PMNs in cancer patients, we analyzed Arg1 expression and activity in these two myeloid subsets comparing CML Gr-MDSCs to autologous PMNs." (PMID 25014230, 2014). "It remains to be explored whether erythroid Arg1 overexpression in mice would instead confer immunomodulatory protective effects or instead exacerbate infection or cancer outcomes by inhibiting T-cell responses." (PMID 40729962, 2025). "In response to classic chemotherapy, cancer cells, like melanoma cells, secrete more EVs able to restart cancer growth in in vivo systems, specifically by enhancing arginase 1 and IL10 in stromal cells and stimulating the transcription of genes involved in the DNA repair process." (PMID 40806235, 2025). "ARG1 regulates the cancer cell immune escape through various manners in TME." (PMID 40659985, 2025). "Our study of cancer cachexia proposes a novel mechanism for cachexia and emphasize the need to further explore the role of ARG1-producing myeloid cells in cachexia pathogenesis, as this may pave the way for future therapeutic advancements." (PMID 40474277, 2025). "Increased arginase-1 expression is a poor prognostic factor in various cancer types." (PMID 40358184, 2025). "Furthermore, our study also discovered that under the induction of SPP1, pro-cancer genes such as Arg1 and Nos2 were upregulated in MDSCs, while anti-cancer genes like IL1b and TNFα were downregulated." (PMID 39066845, 2024). "Neutrophils in the cancer environment can impede CD8+ T cell-dependent immune surveillance through various mechanisms, including Kras mutation, SETD2 deficiency-induced H3K36me3 methylation, miR-146a delivery, and the production of NO, GM-CSF, and arginase-1." (PMID 39034411, 2024). "In cancer progression, MDSCs contribute to the suppression of T cells and regulatory T cells through the production of suppressive cytokines such as arginase 1 (Arg1), reactive oxygen species (ROS), and iNOS." (PMID 37637063, 2023). "Thus, IC animals recruited higher total numbers of Ly6G + Arg1 + cells to the Ep in response to Ca infection while IS animals had reduced and delayed Ly6G + Arg1 + recruitment." (PMID 37886517, 2023). "In cancer patients, ARG1 is increased while L-Arginine is decreased in plasma samples." (PMID 37699892, 2023). "However, the medium from LNT‐treated cancer cells induced an increase in iNOS expression and a decrease in that of Arg1 in a dose‐dependent manner (third and fourth rows)." (PMID 37249285, 2023). "In addition, arginase-1, encoded by the ARG1 gene, is also considered as a sensitive and specific immunohistochemical marker of normal cells and benign and malignant neoplasms derived from hepatocytes." (PMID 37443694, 2023). "Arg1 gene expression was induced by the conditioned medium of Rv-treated human cancer cells only." (PMID 35237269, 2022). "Although a number of different M-MDSC– and PMN-MDSC–derived substances have been implicated in lymphocyte suppression in this context, reactive oxygen species (ROS) and arginase 1 (ARG1) have emerged as the 2 entities seemingly responsible for the majority of lymphocyte suppression in cancer." (PMID 36377658, 2022). "OCT4 alone or coexpressed with vimentin, reached statistical significance for OS and 5-year survival, respectively, after pairing with Arginase 1 (ARG1), suggesting that CSC and EMT may be linked, favouring cancer proliferation." (PMID 36358805, 2022). "ARG-1, the molecular marker of the M2 macrophages, is highly prevalent in cancer cells." (PMID 35889289, 2022). "In combination with other immunotherapies, the ARG1 cancer vaccine could likely play a role in future cancer treatment strategies for patients with high levels of ARG1-expressing cells in the TME." (PMID 36330525, 2022).
cancer (continued). "Because GM-CSF is secreted by Kras-expressing PDA cells, impacts macrophage Arg1 expression, and activates PI3K, we postulated that cancer cell GM-CSF may be activating macrophage Arg1 expression through the PI3K–AKT pathway." (PMID 35156921, 2022). "Therefore, both innate and adoptive immune mechanisms are strongly affected by ARG1 activity in cancer." (PMID 36010962, 2022). "Based on the previous pre-clinical and clinical vaccination trials targeting proteins involved in immune regulation from CCIT-DK, we planned a trial with a therapeutic ARG1 peptide vaccine for patients with high MDSC-expressing cancers treated at the Oncology Department at Herlev Hospital." (PMID 36330525, 2022). "HCC cells from 5 to 6 patients and the primary hepatocytes were stained with CK-18, ALB, ARG-1 (biomarkers of hepatocyte and hepatocarcinoma cells) and AFP (biomarker of hepatocarcinoma cells), with cancer-associated fibroblasts (CAFs, from HCC sample) as the negative control." (PMID 34776939, 2021). "In addition, arginase-1 (ARG1), another key enzyme driving immunosuppression, was also detected in exosomes from several cancers." (PMID 34078376, 2021). "Hence, the use of inhibitors of arginase-1 and indolamine- 2, 3- dioxygenase-1 enzymes, which catabolise L-arginine and tryptophan, respectively, are now exploited as new cancer immunotherapy strategies." (PMID 33747948, 2021). "Because of their ability to interact with cancer cells, as well as their outstanding capability to travel to different tissues, neutrophils could be used as vehicles to carry arginase-1 to the metastatic site." (PMID 34439330, 2021). "Besides pro inflammatory effect, neutrophils also suppress anti-cancer immunity, by releasing arginase-1 as an inhibitor of T cells function." (PMID 34837913, 2021). "Indeed, the inhibition of ARG1/2 activity has yielded positive results across numerous cancer models by reducing myeloid-driven immune suppression." (PMID 33401460, 2021). "Interestingly, we recently demonstrated a unique STAT3-dependent expression of ARG1 in a subset of cancer patient-derived monocytes." (PMID 32133298, 2020). "Interestingly, the immune system itself can target regulatory cells, and naturally occurring T cells specific to epitopes from pivotal immune regulatory proteins such as indoleamine 2,3-dioxygenase, PD-L1, PD-L2 and ARG1 have been described in cancer patients." (PMID 32630667, 2020). "The expression of ARG2, but not ARG1, has been shown to be upregulated by hypoxia and implicated in mediating hypoxia-induced cancer cell proliferation." (PMID 32872669, 2020). "The Arg-1 specificity in the diagnosis of cancer was somewhat higher than that of HepPar-1." (PMID 32854754, 2020). "Post treatment reduction of myeloid Arginase 1 levels association with long RFS is consistent with the long held belief that increased Arginase 1 and elevated NO levels contributes to cancer immune escape." (PMID 32161584, 2020). "Moreover, the cancer-related increase in arginase-1 activity in macrophages further supports cancer growth by inducing immunosuppression." (PMID 32521714, 2020). "Consistently, the polarized THP-1 cells revealed the induced amounts of M1 marker (iNOS and CD80) and the reduced amounts of M2 marker (CD163 and Arginase-1) while reacting with the cancer cells those were pretreated with Oligo-Fucoidan or in combination with cisplatin." (PMID 32059469, 2020). "For the first time, our data demonstrated that ARG1 is expressed in human cancer-programmed monocytes, with the suppressive CD14+ monocytes expressing higher amount of the protein and presenting a unique pattern of staining, making them trackable from other circulating monocytes." (PMID 31533831, 2019). "Interestingly, the expression of Arg1 in macrophages was increased substantially by lactate secreted by cancer cells under hypoxia, but only slightly under normoxia." (PMID 31324019, 2019).